DDX5 (DEAD-box helicase 5)
Diseases named in the same sentence as DDX5 in open-access papers (continued):
Sharing a sentence is not in itself a finding about the gene and the disease.
glioma (11 papers, 2016 to 2023). A benign or malignant brain and spinal cord tumor that arises from glial cells (astrocytes, oligodendrocytes, ependymal cells). "DUSP5 negatively regulates the ERK proliferation pathway; thus, overexpression of DDX5 observed in gliomas causes hyperactivation of ERK through downregulation of DUSP5, promoting cancer proliferation." (PMID 35954483, 2022). "In glioma patients, DDX5 expression is significantly associated with poorer overall survival." (PMID 35992805, 2022). "In gliomas, DDX5 can interact with p50 to enhance its accumulation and transcriptional activity in the nucleus, leading to promoting tumor growth." (PMID 36996491, 2023). "In all the tested cancer cell lines, including lung, esophageal, colorectal, bladder, bone, and glioma cells, DDX5 protein was repressed in response to hypoxia (< 0.1% O2)." (PMID 37013907, 2023). "Mechanistically, LINC01116 directly binds to and recruits DDX5 to the IL-1β gene promoter in glioma cells to increase the expression of IL-1β which in turn promotes glioma progression and recruits neutrophil to glioma." (PMID 37596619, 2023). "LINC01116 recruits DDX5 to the IL-1β promoter and activates IL-1β expression to promote neutrophil recruitment and glioma proliferation." (PMID 35992805, 2022). "Published studies have shown that DDX5 enhances glioma cells invasion by negatively regulating DUSP5." (PMID 32694946, 2020). "In glioma, DDX5 binds with NF-kB p50 and enhances its nucleus accumulation and transcriptional activity, leading to increased tumor growth." (PMID 28216662, 2017). "In NSCLC and glioma, DDX5 was significantly overexpressed in cancerous tissues compared with normal adjacent tissues and predicted poor prognosis." (PMID 28216662, 2017). "DDX5 promotes glioma cell proliferation and tumor growth through the direct regulation of the NF-kB transcription factor p50." (PMID 27835882, 2016). "In glioblastoma, DDX5 has been observed to bind the N-terminus of the NF-κB p50 subunit, increasing the transcriptional activity of the p50 target genes and stimulating the growth of glioma cells." (PMID 35954483, 2022). "LINC01116 is overexpressed in gliomas and could recruit DDX5 to the IL-1β promoter region to activate its transcription." (PMID 35954483, 2022). "LINC01116 can promote tumor proliferation and neutrophil recruitment through DDX5-mediated regulation of IL-1β in glioma cells; and melanoma-derived factors may alter the maturation and activation of differentiated tissue-resident dendritic cells." (PMID 34966411, 2021). "Meanwhile, we confirmed that the level of DDX5 enrichment in the IL-1β promoter region of glioma cells was significantly decreased after knockdown of LINC01116, indicating that LINC01116 could recruit DDX5 to the IL-1β promoter region to activate transcription." (PMID 32358484, 2020). "For example, DDX5/DDX17 expression significantly correlates with the WHO grade and histological type of glioma patients." (PMID 35992805, 2022).
hepatocellular carcinoma (10 papers, 2019 to 2024). A malignant tumor that arises from hepatocytes. "It has been demonstrated that during HBV replication, DDX5 is downregulated, and reduced DDX5 in HBV-associated hepatocellular carcinoma (HCC) is related to poor prognosis." (PMID 36506030, 2022). "DDX5 sensitizes hepatocellular carcinoma (HCC) to sorafenib by inhibiting Wnt/β-catenin signaling and inducing ferroptosis, offering a promising therapeutic strategy when overexpressed in combination with multi-tyrosine kinase inhibitors (mTKIs)." (PMID 39315094, 2024). "RNA helicases also have known roles in cancer; in particular, DDX5 promotes GC cell proliferation, and DDX17 hepatocellular carcinoma progression via inhibiting Klf4 transcriptional activity." (PMID 35566209, 2022). "DDX5 downregulation is observed during HBV replication and in poor prognosis HBV-related hepatocellular carcinoma (HCC)." (PMID 37395407, 2023). "Existing evidence indicates that DDX5, DDX27, and DDX39 played a major role as oncogenes in gastric cancer and hepatocellular carcinoma (HCC)." (PMID 35723050, 2022). "Given DDX5’s function in genome stability and DNA damage repair reviewed above, we will further expound on the DNA damage repair functions in two cancer types, pancreatic ductal adenocarcinoma (PDAC) and hepatocellular carcinoma (HCC)." (PMID 37596619, 2023).
lung carcinoma (8 papers, 2013 to 2023). "Next, H1299 human lung carcinoma cells were stably transfected with pRTS-1 constructs, conditionally expressing HA-tagged Ddx5 wild-type (WT) or Ddx5 mutants in a doxycycline-dependent manner." (PMID 23788676, 2013). "There are researches revealed that DDX5 and DDX3X were identified as regulators in lung cancer." (PMID 35864588, 2022).
non-small cell lung carcinoma (8 papers, 2016 to 2024). A group of at least three distinct histological types of lung cancer, including non-small cell squamous cell carcinoma, adenocarcinoma, and large cell carcinoma. "FGD5-AS1 sponges miR-493-5p, rendering miR-493-5p incapable of targeting DDX5 and promoting the development of non-small cell lung cancer." (PMID 35992805, 2022). "For example, DDX5 promotes the proliferation of non-small-cell lung cancer cells for tumorigenesis by directly interacting with β-catenin to promote the transcription of cyclin D1 and c-Myc." (PMID 27835882, 2016). "Indeed, the knockdown of DDX5 impairs the proliferation of esophageal cancer cells and non-small-cell lung cancer cells." (PMID 39769018, 2024). "DDX5 promotes cyclin D expression in non-small-cell lung cancer through the β-catenin axis." (PMID 35954483, 2022). "Moreover, DDX5 can promote cell proliferation by increasing the transcription of cyclin D1 in non-small cell lung carcinoma." (PMID 34207140, 2021).
cervical carcinoma (7 papers, 2022 to 2025). A carcinoma arising from either the exocervical squamous epithelium or the endocervical glandular epithelium. "A special case is represented by the transcription factor YY1, which was found to interact with both DDX3X and DDX5 in cervical cancer, where it can act both as an oncosuppressor and an oncogene, depending on the subset of genes that are activated." (PMID 35954483, 2022). "Other regulatory molecular mechanisms contributing to the anticancer action of 1,25(OH)D3′s in cervical cancer cells include the downregulation of oncogenic voltage channels, upregulation of DDX5 RNA helicase action, and increased biogenesis of microRNAs regulating cancer pathways." (PMID 36979850, 2023). "DDX5 acts as an oncogene in cervical cancer, which raises the question of whether it exerts its tumor-promoting function by enhancing the oncogenic activity of YY1 or repressing its oncosuppressive role." (PMID 35954483, 2022). "Knockdown of both DDX5 and DDX17, in human cervical carcinoma cells suppressed cellular proliferation indicating their association with abnormal cell growth." (PMID 35237661, 2022). "Yang and colleagues reported the tyrosine phosphorylation of DDX5 in K562 cells as well as various cancer cells, including lung, colorectal, liver, breast, and cervical cancers, but not in untransformed cells." (PMID 38612503, 2024).
leukemia (7 papers, 2017 to 2024). A malignant (clonal) hematologic disorder, involving hematopoietic stem cells and characterized by the presence of primitive or atypical myeloid or lymphoid cells in the bone marrow and the blood. "Thus, DDX5 expression determines the susceptibility of different leukemia subtypes to 2F5." (PMID 35992805, 2022). "The results obtained showed that the levels of basal expression of DDX5 in different leukemia cell lines were also different; the baseline level of DDX5 in APL cell lines was much higher than that in the T-ALL cell line." (PMID 35954483, 2022). "The expression of DDX5 was detected in five different leukemia cell lines, and corresponding healthy control cells." (PMID 32690860, 2020). "Our results showed that the basal expression levels of DDX5 in different leukemia cell lines were also different, DDX5 basal level in APL cell lines were much higher than that in T-ALL cell line." (PMID 32690860, 2020). "Knocking down DDX5 reduces the expression of the Notch signaling gene in leukemia cells and inhibits the proliferation of leukemia cells, resulting in a reduction in the growth of leukemia xenotransplants and promoting cell apoptosis." (PMID 35992805, 2022). "The reasons for these different outcomes may be explained by variance in basal DDX5 expression in different leukemia cell lines; for example, DDX5 expression in APL cell lines is significantly higher than that in T-ALL cell lines." (PMID 35992805, 2022).
acute myeloid leukemia (6 papers, 2020 to 2025). Acute myeloid leukemia (AML) is a group of neoplasms arising from precursor cells committed to the myeloid cell-line differentiation. "Inhibition of DDX5 expression in acute myeloid leukemia (AML) significantly reduces cancer cell proliferation in vitro and progression in vivo." (PMID 35954483, 2022). "DDX5 has been recognized to be a novel target to suppress acute myeloid leukemia (AML)." (PMID 32690860, 2020). "DDX5 was shown to promote the progression of acute myeloid leukemia (AML), and DDX5 inhibition can induce apoptosis of AML cells without any toxicity to bone marrow cells." (PMID 37596619, 2023).
COVID-19 (6 papers, 2021 to 2023). A disease caused by infection with severe acute respiratory syndrome coronavirus 2. "Proteomic analysis of the virus-host protein interaction network revealed that 13 splicing factors are down-regulated in COVID-19 patients, including DEAD-box 5(DDX5), DDX17 and DDX1, indicating that SARS-CoV-2 infection result in serious dysfunction of host splicing mechanism." (PMID 38035086, 2023). "Interestingly, among these known virus-host PPIs, 13 splicing factors were downregulated in the COVID-19 patients, including three members of RNA helicase, DDX5, DDX17 and DDX1." (PMID 35421082, 2022). "Our results showed that six spliceosomal component proteins (DDX5, DDX17, DDX39B, PRPF6, SNRNP40, and SNRNP200) were significantly down-regulated in COVID-19 patients." (PMID 35421082, 2022). "In addition, a recent study has found that DDX5 is involved in the regulation of SARS-CoV-2 replication, thereby identifying the ability of the immune memory of COVID-19 vaccine." (PMID 37007947, 2023). "Ultimately, EEF1A1, EGR1, UBA52, DDX5 and IRF8 might be the key shared pathogenesis-related genes in COVID-19 and asthma." (PMID 36575422, 2022).
glioblastoma (6 papers, 2021 to 2023). The most malignant astrocytic tumor (WHO grade IV). "It has been documented that tyrosine (Y) 593/Y595‐double phosphorylated DDX5 protects glioblastoma cells from apoptosis, and Y593‐phosphorylated DDX5 promotes epithelial‐to‐mesenchymal transition (EMT) in CRC cells." (PMID 35604033, 2022). "The double tyrosine phosphorylation of DDX5 downstream of platelet-derived growth factor signaling is associated with the inhibition of CASP8 cleavage and resistance to TRAIL-induced apoptosis in T98G glioblastoma cells." (PMID 35626643, 2022). "To explore potential links between DDX5 and hypoxia in cancer, we asked whether DDX5 expression and a validated hypoxia signature correlated in TCGA cancer patient cohorts (glioblastoma, breast, colorectal, bladder, lung adenocarcinoma, and lung squamous cell carcinoma)." (PMID 37013907, 2023). "For example, DDX5 has been most intensely studied for its role in splicing, gene expression, and oncogenesis; however, beyond these roles, the phosphorylation of DDX5 can inhibit TRAIL-induced apoptosis in glioblastoma cells." (PMID 35626643, 2022).
thyroid cancer (6 papers, 2022 to 2023). "SLC26A4 promotes the degradation of DDX5 through the ubiquitin–proteasome pathway to inhibit thyroid cancer metastasis." (PMID 35992805, 2022). "SLC26A4-AS1 suppressed thyroid cancer metastasis by acting as a scaffold of DDX5 and TRIM25." (PMID 37582794, 2023). "Additionally, it has been reported that the lncRNA SLC26A4-AS1 suppresses DNA repair and thyroid cancer metastasis through its interaction with DDX5 and promotion of DDX5 degradation by the E3 ligase TRIM25." (PMID 37596619, 2023). "LncRNA SLC26A4-AS1 promoted DDX5 degradation via ubiquitin-proteasome pathway in thyroid cancer." (PMID 35541917, 2022). "Moreover, in thyroid cancer, knockdown of TRIM28 inhibits P68/DEAD box protein 5(DDX5)-mediated Wnt/β-catenin signaling pathway." (PMID 36756159, 2023). "DDX5 interacts with the transcription factor E2F1 and promotes thyroid cancer development." (PMID 35954308, 2022). "In human thyroid cancer cells, SLC26A4-AS1 silencing enhances the interaction between DDX5 and the transcription factor E2F1; then, the DDX5-E2F1 complex binds to the MRN gene promoter and thus stimulates the MRN/ATM-dependent DNA DSB signaling cascade and thyroid cancer metastasis." (PMID 35992805, 2022).
Infertility (5 papers, 2021 to 2024). "Here, we generated Ddx5 conditional knockout mice by using Mvh‐Cre to delete Ddx5 from embryonic period and found that the infertility of adult male mice after Ddx5 loss was due to low survival of gonocytes." (PMID 33666296, 2021). "To assess the reason of infertility in Ddx5‐deficient male mice, we observed that the testes of Ddx5‐/‐ mice were significantly smaller and lighter than those of wild‐type and Ddx5+/‐ mice." (PMID 33666296, 2021). "The phenotype that Ddx5‐/‐ adult male mice were completely devoid of germ cells is consistent with Sertoli cell‐only syndrome associated with human infertility." (PMID 33666296, 2021). "In this study, we report that Ddx5 is required for male germ cell development and Ddx5‐deficient male mice are infertile due to loss of gonocytes in neonates." (PMID 33666296, 2021). "Furthermore, Ddx5 knockout resulted in a complete loss of germ cells, containing only Sertoli cells within 6 days after birth, and led to azoospermia and infertility in male adults." (PMID 33666296, 2021). "Homozygous DDX5-/- mice suffered from embryonic lethality or infertility." (PMID 38182816, 2024). "The authors demonstrated that (i) germ cell-specific DDX5 KO (DDX5-/-) leads to infertility in adult male mice due to the complete elimination of germ cells; (ii) male germ cells gradually disappeared in DDX5(-/-) mice from E18.5 to P6; and (iii) DDX5 ablation impeded the proliferation of gonocytes." (PMID 37596619, 2023). "Disruption of Ddx5 in adult spermatogonia results in infertility." (PMID 33666296, 2021). "STRING and Cytoscape analyses presented seven genes, i.e., DDX5, TNP2, DDX3Y, TDRD6, SOHL2, DDX31, and SYCP3, as the hub genes involved in infertility with VASA co-function and protein–protein interaction." (PMID 36241908, 2022). "The ratio of infertility genes expression: DDX5, TNP2, DDX3Y, TDRD6, SOHL2, DDX31, and SYCP3 in infertility cell (azoospermia) in comparison to a normal cell." (PMID 36241908, 2022). "We found that Ddx5-/- mice died during the embryonic stage (date not shown), whereas a previous study showed that homozygous Ddx5-/- mice with embryonic lethality or infertility displayed blood vessel malformations, suggesting a homozygous loss of function." (PMID 33909701, 2021). "Ddx5 deletion leads to a complete lack of germ cells and infertility in male adults." (PMID 33666296, 2021).
liver cancer (5 papers, 2020 to 2023). An epithelial or non-epithelial malignant neoplasm that arises from the liver. "Intriguingly, we found that sorafenib treatment, 1–3 days, of HepAD38 cells and various human liver cancer cell lines resulted in progressive downregulation of DDX5." (PMID 38036507, 2023). "TINCR sponges miR-218-5p to prevent miR-218-5p from targeting DDX5, thus promoting the progression of liver cancer." (PMID 35992805, 2022). "One possibility for such observations (in the liver cancer reviewed above) that contradicts the oncogenic role of DDX5 in other cancer types could be that DDX5 has high genome DNA repair capacity in HCC to control HCC malignancy in the defined conditions." (PMID 37596619, 2023). "The role of DDX5 in liver cancer was discussed in our 2021 review." (PMID 37596619, 2023). "DDX5 overexpression induces autophagy in liver cancer cells." (PMID 35992805, 2022). "In liver cancer, DDX5 overexpression significantly reduces tumorigenesis, and patients with low DDX5 expression may have a poorer prognosis after treatment." (PMID 35992805, 2022). "Additionally, expression of Disheveled, DVL1, a key regulator of Wnt pathway activation, was significantly higher in liver cancer cells with low DDX5 expression, from two independent cohorts." (PMID 33042264, 2020). "Furthermore, transient (siRNAs #1 and #2) knockdown of DDX5 in Huh7 and HepaRG cells also increased luciferase expression from the TOPFlash reporter, supporting this mechanism is functional in other liver cancer cell lines." (PMID 33042264, 2020). "Moreover, loss of DDX5 either by overexpression of miR106b~25 and miR17~92, stable knockdown of DDX5, or DDX5 siRNA transfection, activate Wnt/β-catenin signaling in various liver cancer cell lines." (PMID 33042264, 2020). "In liver cancer cell lines and preclinical HCC models sorafenib and mTKIs downregulate DDX5, and DDX5KD cell lines exhibit reduced sensitivity to sorafenib." (PMID 38036507, 2023).
osteosarcoma (5 papers, 2019 to 2023). A usually aggressive malignant bone-forming mesenchymal neoplasm, predominantly affecting adolescents and young adults. "In conclusion, our study anticipated that VAMP8 inhibits osteosarcoma metastasis by promoting the proteasomal degradation of DDX5, consequently inhibiting WNT/β-catenin signaling and EMT." (PMID 37405957, 2023). "DLEU1 sponges miR-671-5p, making it impossible for miR-671-5p to target DDX5, thus promoting the progression of osteosarcoma." (PMID 35992805, 2022). "LncRNA DLEU1 inhibits osteosarcoma progression by regulating the function of the miR-671-5p/DDX5 axis." (PMID 34015762, 2021). "Although DDX5 expression in osteosarcoma cells was higher than that in normal bone cells, its expression level was generally lower." (PMID 35992805, 2022).
acute promyelocytic leukemia (4 papers, 2020 to 2025). An aggressive form of acute myeloid leukemia (AML), characterized by arrest of leukocyte differentiation at the promyelocyte stage, due to a specific chromosomal translocation t(15;17) in myeloid cells. "One study analyzed the effects of the anti-DDX5 monoclonal antibody 2F5 on acute promyelocytic leukemia (APL)." (PMID 35954483, 2022).
asthma (4 papers, 2022 to 2023). "In addition, DDX5 is known to be a hub gene of the cilia module in asthma and a regulator of ERBB2, which is associated with epithelial repair processes in asthma patients." (PMID 37875944, 2023). "As an example, the SNP rs1991401, which is associated with myopia, asthma and blood traits, affects the TATA-box in the promoter of the DDX5 gene." (PMID 37403796, 2023). "After applying the Bonferroni correction (Psmr < 2.08 × 10–6) and HEIDI threshold (PHEIDI > 0.01), a total of four SMR genes were identified: three SMR genes (AHI, MED24, and DDX5) with the European asthma-GWAS summary and one SMR gene (RPS26) with the Japanese asthma-GWAS summary." (PMID 37875944, 2023). "Among the four SMR genes in the asthmatic eQTL data, two genes, DDX5 and MED24, were not identified in the SMR analysis of the two normal eQTL data, and have not been reported to be significantly associated with asthma in the SMR analysis." (PMID 37875944, 2023).